JAK1 (Janus kinase 1)
Diseases named in the same sentence as JAK1 in open-access papers (continued):
Sharing a sentence is not in itself a finding about the gene and the disease.
melanoma (continued). "Loss-of-function mutations in JAK1 and JAK2 are extensively reported to be the cause of ICB resistance in melanoma patients and gynecologic cancers." (PMID 37275859, 2023). ",6,7,8JAK1 is mutated in approximately 10% of CRC and 6% of skin cutaneous melanoma, with a decrease in survival for melanoma patients with deleterious JAK1 alterations." (PMID 36669486, 2023). "Consistent with this view, JAK1 was found to be critical for inducing resistance to NK cells in melanoma and recurrence of HCC." (PMID 36104718, 2022). "Since the IFN-γ signaling pathway in melanoma cells induces tumor growth arrest and death, mutations of IFNGR1, IFNGR2, JAK1, JAK2, STAT1, and IRF3 lead to insensitivity to anti-tumor IFN-γ activity." (PMID 35432377, 2022). "We identified a JAK1/2-centered network of constitutively active PTKs in IFNγR1KO melanomas, which offers a “personalized” therapeutic target that can be harnessed to treat these ICB-resistant melanomas." (PMID 36008408, 2022). "We show here that the augmented mTOR pathway represents such a key compensatory mechanism, resulting in JAK1/2 activation in IFNγR1KO melanoma." (PMID 36008408, 2022). "IFNγR1KO melanomas harbor a network of constitutively active protein tyrosine kinases centered on activated JAK1/2." (PMID 36008408, 2022). "The mutation of JAK1/JAK2 results in PD-L1 depletion and insensitivity to IFN-γ, ultimately causing the primary resistance to anti-PD-1 treatment in melanoma and colorectal cancer patients." (PMID 36189283, 2022). "Here the authors report that melanoma cells with knockout of IFNγR1 show constitutive JAK1/2 activation and that the JAK1/2 inhibitor ruxolitinib can overcome resistance to anti-CTLA-4 therapy." (PMID 36008408, 2022). "Cytokine-inducible SH2-containing protein (CIS) was found to interact with JAK1, induce proteasomal degradation in NK cells and then mediate resistance to melanoma and prostate and breast cancer metastasis." (PMID 36104718, 2022). "To establish the clinical relevance of our findings, we rationalized that IFNGR1Low SKCMs with impaired IFN-γ signaling and patient melanomas resistant to ICBs would house activated mTOR and JAK1/2 to some extent." (PMID 36008408, 2022). "To determine the relevance of these residues for the STUB1-mediated regulation of IFNγ-R1 and JAK1, we generated melanoma cell clones deficient in both IFNGR1 and JAK1 (IFNGR1-KO + JAK1-KO) in either a wildtype or STUB1-deficient background." (PMID 35395848, 2022). "In melanoma patients, loss-of-function mutations in IFN-gamma encoding genes or Janus kinase 1 (JAK1) and JAK2 are associated with acquired resistance to anti-PD-1 therapy." (PMID 34502043, 2021). "The same distribution was observed for sgRNAs targeting Jak1 and Jak2, which mediate the response to anti-PD-1 therapy in melanoma patients." (PMID 34853298, 2021). "Similar to PD-L1, the expression of CTLA-4 in human melanoma cells is also regulated by IFN-γ through the JAK1/2-STAT1-IRF1 pathway." (PMID 34620200, 2021). "JAK1 signaling regulates actomyosin contractility by regulating the level of phosphorylated-MLC2 in both melanoma cells and CAFs, the latter of which lead SCC invasion." (PMID 32546182, 2020). "The inhibition of Jak1/2 significantly promoted the elongated, mesenchymal migratory phenotype of five tested melanoma cell lines in 3D collagen." (PMID 32872349, 2020). "As for inactivating mutations in JAK1 or JAK2, these have been also linked to resistance to anti-PD-1 therapy in melanoma, but more research to evaluate their response to anti-PD-1 agents in CRC." (PMID 32090113, 2020). "Here using a genome-wide CRISPR screen in B16.SIY melanoma cells, we confirm Ifngr2 and Jak1 as important genes conferring sensitivity to T cell-mediated killing in vitro." (PMID 32001684, 2020). "Initially, we tested the effect of IFN signalling suppression by Ruxolitinib, a Jak1/2 inhibitor, on a panel of amoeboid and mixed-morphology melanoma cells lines." (PMID 32872349, 2020).
melanoma (continued). "Mechanisms of acquired resistance to checkpoint inhibitors include loss of IFNγ-transducing signaling pathways JAK1 and JAK2, loss of antigen presentation (B2M) and activation of the PTEN/PI3K pathway in pembrolizumab-treated melanoma patients." (PMID 31647026, 2019). "Deletion of interferon γ receptors, JAK1, JAK2 and STAT1 in mice with melanoma resulted in loss of PD-L1 expression and resistance to PD-1 inhibition." (PMID 35582566, 2019). "Loss-of-function mutations in JAK1 and JAK2 have been associated with primary and acquired resistance to PD-1 blockade in melanomas." (PMID 29082853, 2017). "We demonstrated that IFNγ secreted by GM-ADSCs is able to directly affect melanoma cells in vitro, probably through activation of JAk1/Stat1 pathway." (PMID 25428727, 2014). "JAK1/2 mutations have also been associated with accelerated tumor growth post-ICI due to defective MHC-I expression and resistance to T cell cytotoxicity in melanoma." (PMID 40873541, 2025). "Importantly, IFNγ is known to induce PD-L1 expression in melanoma cells through the JAK1/2-STAT1/3-IRF1 axis, and there are indications that some melanoma cell lines display increased IFNγ-induced PD-L1 expression when dedifferentiated." (PMID 39736644, 2024). "The melanoma cell lines that had JAK1/2 homozygous loss of function mutations did not respond to IFN-γ." (PMID 39530091, 2024). "In keeping with the dual role of IFN signaling in both inhibiting and promoting anti-tumor immunity, treatment of YUMM3.3 melanoma-bearing mice with JAK1/2 inhibitors drastically accelerated the growth of Ctrl tumors, thereby minimizing the difference compared to the growth rate of βA tumors." (PMID 38304252, 2023). "Interestingly, tumor response to IFN-γ, such as APLNR interaction with JAK1 in melanoma cells, is crucial for CAR-T cytotoxicity only in solid tumors but not hematological tumors." (PMID 37275859, 2023). "Losses and mutations in these genes have been linked to primary and acquired resistance to PD-1 blockade in melanoma, suggesting that melanoma cells become insensitive to the antiproliferative effects of IFNγ (via JAK1/2 alterations) or lose antigen presentation (via B2M alterations)." (PMID 36977461, 2023). "Similarly, functional loss of JAK1/JAK 2 mutations has been found in melanoma samples and melanoma cell lines, which fail to respond to IFN-γ signaling and result in lack of PD-L1 expression." (PMID 35842707, 2022). "Whole-exome sequencing of human melanoma tissues and the human melanoma cell line revealed that acquired resistance can result from loss-of-function mutations of IFNGR1, IFNGR2, JAK1, JAK2, STAT1, and IRF3 from the IFN-γ signaling pathway and β2M from antigen presentation pathway." (PMID 35432377, 2022). "Moreover, it was demonstrated that melanoma with JAK1/2 mutants also block MHC class I upregulation by IFN-γ, similar to that of β2M mutants." (PMID 35432377, 2022). "Besides, researchers also point out that human melanoma cell lines are insensitive to interferon (IFN)-induced antitumor effects after JAK1/2 knockout." (PMID 34587898, 2021). "3pRNA treatment even forced de novo HLA-I APM expression in patient-derived JAK1 mutant melanoma cells and restored their T cell sensitivity, demonstrating that activated RIG-I triggered an IFN-independent salvage pathway capable of overcoming tumor cell-intrinsic T cell resistance." (PMID 33554047, 2021). "Melanoma cells with JAK1/2 deletion are resistant to IFN-induced anticancer activity, whereas melanoma cells with B2M loss block melanoma cells from being recognized by antigen-specific T cells and maybe therefore resistant to cytotoxicity." (PMID 34804979, 2021). "Certain genetic mutations in melanoma, including JAK1, JAK2, B2M and PTEN, etc., correlate with negative treatment response of PD-1 blockade therapy, while BRCA2 mutations were reported enriched in melanomas responsive to this treatment." (PMID 32333081, 2020).
melanoma (continued). "STAT5 activation is induced by the EGF/JAK1 axis in melanoma cell lines." (PMID 31569642, 2019). "In addition, JAK1 mRNA expression was lower in bladder cancer, gastric cancer, lung cancer, ovarian cancer, prostate cancer, melanoma, and lymphoma tumors." (PMID 31790361, 2019). "Additionally, an intriguing pre-clinical observation made in immune-competent mice challenged with melanoma demonstrates that acquired resistance to immune checkpoint blockade is reversed by inhibiting JAK1/JAK2 signaling." (PMID 30992475, 2019). "Furthermore, loss-of-function mutations in the upstream IFNγ-signaling regulators JAK1 and JAK2, concurrent with deletion of the wild type alleles, have been identified in two melanoma patients who failed anti-PD-1 therapy." (PMID 29977240, 2018). "Loss-of-function mutations in the interferon-receptor-associated Janus kinase 1 (JAK1) and/or Janus kinase 2 (JAK2) genes in melanoma and mismatch repair-deficient colon cancer have been implicated in acquired resistance, or possibly even primary resistance, to PD-1 inhibition." (PMID 28428947, 2017). "At the gene expression-level, we observed similar associations with JAK1 mutations in our series of primary MSI+ CRCs, including up-regulation of transcriptional signatures associated with innate resistance to anti-PD-1 treatment in melanoma." (PMID 28539123, 2017). "In melanoma, one patient without a clinical response to PD-1 blockade and increased T-cell response showed a loss of function JAK1 mutation that unables PD-L1 upregulation." (PMID 27213585, 2016). "Endothelial STING and JAK1 expression was significantly associated with immune cell infiltration in patients with cancer, and STING palmitoylation level correlated positively with CD8+ T cell infiltration around STING-positive blood vessels in tumor tissues from patients with melanoma." (PMID 39817453, 2025). "Recent studies using the melanoma mouse model demonstrated that JAK1/2 knockout resistance could be overcome with anti-PD-1 Ab in combination with the TLR9 agonist, which activates TLR9-type IFN signaling, thereby increasing infiltration of T cells and NK cells in the tumor." (PMID 35432377, 2022). "Similarly, truncation in the β2-microglobulin gene resulting in defects in MHC-I-mediated antigen presentation and loss-of-function mutations to JAK1 or JAK2, implying defects to the transduction of antiviral IFN signals; mediate resistance to PD-1 blockade in melanoma." (PMID 33668131, 2021). "Such down regulation, which was observed in melanoma and colorectal cancer, is associated with increased metastatic propensity and with the generation of an immune-privileged TME; (ii) perturbations to JAK/STAT1 signaling including epigenetic silencing and inactivating mutations in JAK1." (PMID 33668131, 2021). "Using CRISPR/Cas9 genome editing we generated JAK1, JAK2 and B2M knockout (KO) sublines of the murine MC38 carcinoma, a model of high mutational load cancer that responds well to anti-PD-1, as well as of human MART-1-positive melanoma cell lines, tested using in-vitro T cell co-culture systems." (PMID 30400822, 2018). "An intriguing pre-clinical observation in an immune-competent melanoma model is that acquired resistance to ICI blockade could be overcome by inhibiting JAK1/JAK2 signalling, suggesting that JAK/STAT signalling may have a more complex role in mediating response and resistance to ICI." (PMID 29319049, 2018). "Intriguingly, in B16F10 melanoma cells, PAI-1 promotes the release of soluble PD-L1 through JAK1/TYK2–STAT3 signaling, thereby suppressing CD8+ cytotoxic T-cell activity in a JAK-dependent manner." (PMID 41008624, 2025). "In melanoma, PAI-1 promotes PD-L1 expression in both tumor cells and stromal cells via the JAK1/STAT3 pathway." (PMID 41008624, 2025). "Western blot analysis confirmed MBP significantly inhibited the phosphorylation of JAK1 and STAT1 in melanoma cells." (PMID 40508400, 2025).
melanoma (continued). "Previous studies have demonstrated that IFNγ-induced PD-L1 expression is reliant on JAK1/JAK2 activity, and that PD-L1 promoter activity and subsequent expression is mainly influenced by STAT1/STAT3 and IRF1 in IFNγ treated melanoma cells." (PMID 39736644, 2024). "Microglia cells showed significantly higher mRNA expression for JAK1, STAT3, and SOCS3 compared to melanoma cells." (PMID 37296634, 2023). "Truncating mutations, homozygous deletions, and low protein levels of IFNGR1, IFNGR2, JAK1, JAK2, STAT1, and IRF1 in melanoma patients result in shorter survival than that of patients with wild-type IFNγ signaling genes." (PMID 34385592, 2022). "Inhibiting activated JAK1/2 with Ruxo induces selective suppression of IFNγR1KO melanomas, providing a “targeted” therapy to treat these ICB-resistant melanomas." (PMID 36008408, 2022). "In direct correlation, human melanomas with reduced IFN-γ signaling or ICB resistance exhibit upregulation of target genes in the mTOR and JAK1/2 pathways, indicative of their activation." (PMID 36008408, 2022). "In human melanoma cells, EGF treatment can promote STAT5 activation via tyrosine-protein kinase Src (Src) and Janus kinase 1 (JAK1) signaling leading to STAT5 nuclear translocation along with upregulation of the STAT5 target, Bcl-2, an antiapoptosis protein." (PMID 34067095, 2021). "OSM is a cytokine belonging to the IL-6 family, and in the A375 human melanoma cell line, OSM receptor signaling is mediated by JAK1, JAK2, and tyrosine kinase 2 signaling via STAT3 and STAT5b." (PMID 34067095, 2021). "The inhibition of Janus kinase 1 (JAK1) activity due to ubiquitination by RNF125 decreased EGFR expression at the transcriptomic and protein levels, overcoming BRAFi resistance in melanoma cells." (PMID 33800394, 2021). "The IFN-γ -JAK1/JAK2-STAT1/STAT2/STAT3-IRF1 axis, a key regulator of IFN-mediated PD-L1 expression in melanoma cells, seems to be a good therapeutic option." (PMID 33672515, 2021). "In melanoma cells, the IFN-γ-JAK1/JAK2-STAT1-IRF1 axis regulates PD-L1 expression as melanoma cells can mediate adaptive resistance by upregulating PD-L1 expression in response to IFN-γ released by CTLs." (PMID 32322256, 2020). "Chromosomal alterations and subsequent inactivating mutations in genes of the IFNγ signalling cascade, most often JAK1 or JAK2, protect melanoma cells from anti-tumour IFNγ activity." (PMID 28561041, 2017). "Five pathways wereenriched for genes in the module d-1 (MAPK1, MITF,RAF1, JAK1, and STAT3):pancreatic cancer (P=5.47E-04), melanoma (P=8.52E-03), melanogenesis (P=1.48E-02),acute myeloid leukemia (P=7.67E-03), and cancer pathways (P=3.69E-03)." (PMID 26840709, 2016). "In particular, this transcriptional regulation involves the JAK/STAT pathway (JAK1, LIF, and IL11), which is a strong regulator of contractility in melanoma." (PMID 26526369, 2015). "Despite this, we show that the JAK1/2 inhibitor, AZD1480, is able to inhibit tumor growth and prolong survival in a murine melanoma model." (PMID 25149535, 2014). "For example, in patients with melanoma and CRC patients with elevated TMB who did not respond to anti-PD-1 therapy, homozygous loss-of-function mutations in JAK1/2 were identified, which resulted in deficient PD-L1 expression and reduced T-cell infiltration." (PMID 40075727, 2025). "Both JAK1 and JAK2 knockout melanoma cells are insensitive to anti-PD-1 and anti-CTLA-4 therapy." (PMID 40108693, 2025). "Surprisingly, melanoma cells lacking IFNGR1 exhibited activated JAK1/2, which was a consequence of increased mTOR activity." (PMID 40108693, 2025). "By inhibiting the aberrantly active JAK1/2, Ruxo reprograms the “cold” TILs and selectively suppresses IFNγR1KO but not scrambled control melanoma, offering a potential “targeted” therapy for ICB resistance." (PMID 36640142, 2023).
melanoma (continued). "To explore if activated JAK1/2 could serve as attractive therapeutic targets for ICB resistance, we treated melanoma-bearing mice with Ruxolitinib (Ruxo), an FDA-approved JAK1/2 inhibitor for myeloproliferative neoplasms (MPN) and other pathologies." (PMID 36640142, 2023). "Surprisingly, IFNγR1KO melanomas harbor an aberrantly active mTOR-JAK1/2 axis, which, when targeted with an FDA-approved JAK1/2 inhibitor Ruxo, results in potent and selective suppression of IFNγR1KO but not scrambled control melanomas, in a T cell and host TNF-dependent fashion." (PMID 36008408, 2022). "Targeting activated JAK1/2 with Ruxo selectively suppresses IFNγR1KO but not scrambled control melanomas, coupled with enhanced effector functions (e.g., TNF production) and reduced Treg frequency in TILs." (PMID 36008408, 2022). "Collectively, these results establish that augmentation of mTOR pathway is a major upstream regulator of JAK1/2 activation in melanoma cells lacking functional IFN-γ signaling." (PMID 36008408, 2022). "Genetic alterations in antigen presentation (B2M, HLA-A) and IFNγ signaling (IFNGR, STAT1 and JAK1/2) in non-responding melanoma patients are uncommon, and not restricted to non-responding patients." (PMID 32312968, 2020). "The IL-6/JAK1/signal transducer and activator of transcription 3 (STAT3) axis also controls actomyosin contractility by regulating the levels of phosphorylated-MLC2 in both melanoma cells and CAFs." (PMID 31067787, 2019). "Therefore, we performed Western blots to determine the expression levels of JAK1 and JAK2 during the course of melanoma development." (PMID 25690042, 2015). "A retrospective analysis of patients with melanoma and CRC who did not respond to anti-CTLA-4 or anti-PD-1 therapy revealed these patients had tumors with gene mutations, including JAK1/2 and IFN-γ receptor 1/2 (IFNγR1/2), which are critical for IFN-γ signaling." (PMID 40075727, 2025). "To evaluate whether this enhanced IL-6 signaling mediated JAK1/2 activation, we blocked IL-6 and IL-6R with anti-IL-6 and anti-IL-6R antibodies, respectively, at concentrations that were sufficient to inhibit IL-6-induced p-STAT3 in melanoma cells." (PMID 36008408, 2022). "Moreover, human melanomas with attenuated IFN-γ signaling or ICB resistance exhibit reduced expression of T cell signature genes and alteration of target genes downstream of mTOR and JAK1/2 pathways, suggestive of their activation." (PMID 36008408, 2022). "Evidence suggests a transcriptional regulation of the antigen presentation machinery, as genetic alterations in antigen presentation (B2M, HLA-A) and IFNγ signaling (IFNGR, STAT1 and JAK1/2) remain infrequent in melanomas and are not restricted to non-responding patients." (PMID 35432344, 2022). "Importantly, JAK1/2 inhibition with Ruxolitinib selectively suppresses the growth of IFNγR1KO but not scrambled control melanomas, depending on T cells and host TNF." (PMID 36008408, 2022). "However, mutational inactivation of JAK1, a kinase involved in IFN-I/-II signaling, enables melanoma cells to preserve their immune-evasive HLA-I-low/-negative phenotype in an IFN-rich microenvironment." (PMID 33554047, 2021). "Neither mutation nor gene expression change in JAK1, JAK2, B2M, HLA-A, HLA-B, and HLA-C was observed between pre- and post-treatment tumor samples, which were previously indicated to be associated with resistance to PD-1 antibody treatment in melanoma." (PMID 30872362, 2019). "Notably, deletion of protein tyrosine phosphatase nonreceptor type 2 (PTPN2), a negative modulator of STAT1/JAK1 signaling, enhanced the efficiency of immunotherapy in melanoma tumors by increasing the activation of CD8+ T cells and the IFN-γ signaling pathway." (PMID 34827646, 2021).